CYGB (cytoglobin)
Diseases named in the same sentence as CYGB in open-access papers (continued):
Sharing a sentence is not in itself a finding about the gene and the disease.
renal fibrosis (1 paper, 2020). A final common manifestation of a wide variety of chronic kidney diseases characterized by glomerulosclerosis and tubulointerstitial fibrosis. "Injected R-III localized predominantly in cytoglobin/stellate cell activation-associated protein (Cygb/STAP)-positive cells in the kidney and reduced renal fibrosis." (PMID 33086608, 2020).
scleroderma (1 paper, 2023). Scleroderma is a rare autoimmune connective tissue disorder characterized by abnormal hardening of the skin and, sometimes, other organs. "In our analysis of fibroblasts, FB1 was characterised as a pro-inflammatory or immune-interacting subtype by APOE, CYGB, C7, and IFGBP7 and this subset showed higher levels of CCL19 and PLA2G2A in scleroderma compared to the control." (PMID 37443817, 2023).
steatosis (1 paper, 2020). Increased lipid within the cytoplasm of cells. "The expression profiles of profibrotic genes such as CYGB, ACTA2, PCDH7, DES, COL1A1, and COL1A3 were also significantly up‐regulated in the co‐culture NASH model, when compared with the steatosis model." (PMID 31909357, 2020).
tumor (39 papers, 2006 to 2025). "Cytoglobin (Cygb) is a hexacoordinate protein, associated with the transport of oxygen, nitric oxide scavenging, tumor suppression and protection against oxidative stress and inflammation." (PMID 31920538, 2019). "Moreover, transcriptome analysis revealed the enrichment of multiple cancer-associated pathways in CYGB knockdown G361 cells, demonstrating the tumor-suppressive function of CYGB." (PMID 36009267, 2022). "Furthermore, loss of CYGB in Cygb−/− mice increased their susceptibility to diethylnitrosamine-induced tumorgenesis, indicating a tumor suppressive function of CYGB." (PMID 27489351, 2016). "Conversely, the overexpression of cytoglobin in head and neck cancer patients seems to correlate with increased aggressiveness of the disease, which could be linked to the increased hypoxic state of the tumor." (PMID 35453573, 2022). "Cytoglobin also encodes a tumor suppressor protein, and this may help explain why its expression is higher in tumor tissue from animals fed SD, but lower in tumor tissue from animals fed a KD." (PMID 20831808, 2010). "This subsequently results in a reduced methylation of CYGB promoter, ultimately inhibiting the tumor progression of BCa." (PMID 39227479, 2024). "The downregulation of CYGB expression in cancer cells suggests that it plays a possible role as a tumor suppressor gene." (PMID 36112670, 2023). "CYGB gene is regulated by both promoter methylation and tumour hypoxia in head and neck squamous cell carcinomas with expression correlating with the tumour's biological aggression." (PMID 37721133, 2023). "It has been shown that in some types of cancer, cytoglobin becomes hypermethylated, which silences its expression and promotes tumor progression." (PMID 35453573, 2022). "Together with the observed reduction of ROS-induced DNA damage in Cygb-overexpressing mouse PSCs in vivo as indicated by reduced 8-OHdG, these results demonstrate that CYGB serves a tumor suppressor function via its ROS scavenging ability." (PMID 35504863, 2022). "Reduced CYGB expression through hypermethylation has also been reported in other cancer cell types, indicating that CYGB potentially serves a tumor-suppressive function." (PMID 36009267, 2022). "A previous report has suggested that CYGB promoters are highly methylated in tumor cells with low expressions of CYGB." (PMID 35397613, 2022). "In the non-tumor area, CYGB positivity localized in peri-ductal, peri-vascular, and peri-acinar cells." (PMID 35504863, 2022). "Cytoglobin (CYGB) is a cellular ROS regulator that regulates oxygen homeostasis and acts as a tumor suppressor." (PMID 34830285, 2021). "Cytoglobin (CYGB) is a ubiquitously expressed protein with a protective role against oxidative stress, fibrosis and tumor growth, shown to be transcriptionally regulated under hypoxic conditions." (PMID 34035373, 2021). "The protein encoded by CCL5 belongs to a group of inflammation-relevant genes, while the cytoglobin gene (CYGB) functions as a tumour suppressor gene." (PMID 34112813, 2021). "As a regulator of ROS, cytoglobin (CYGB) plays an important role in oxygen homeostasis and acts as a tumour suppressor." (PMID 33611811, 2021). "CYGB, a member of the vertebrate globin family 38, has multiple functions including tumor suppression, protection against oxidative stress, and reduction of glucose intake in cancer cells 23, 24, 39-41." (PMID 32863941, 2020). "CYGB promoter region was hypermethylated in several types of solid tumors and cancer cell lines compared with normal tissue and non-tumor cell lines." (PMID 30545372, 2018).
tumor (continued). "We further confirmed the involvement of the glucose metabolism pathway in CYGB’s tumor suppression by restoration of GLUT1 and HXK2 expression." (PMID 30545372, 2018). "Recent studies suggested the globin family member cytoglobin (CYGB) as a potential tumor suppressor; however, the mechanism by which CYGB suppresses cancer is elusive." (PMID 30545372, 2018). "Collagen 1A1 (COL1A1), RNA-binding and pre-mRNA Processing Factor (PRPF40A), and Uncoupling Protein 2 (UCP2) were identified as downstream effectors of cytoglobin (CYGB), which was shown implicated in tumour biology." (PMID 28258342, 2017). "We conclude that the CYGB gene is regulated by both promoter methylation and tumour hypoxia in HNSCC and that increased expression of this gene correlates with clincopathological measures of a tumour's biological aggression." (PMID 19568272, 2009). "In the tissue samples, the influence of tumour hypoxia seems greater when CYGB promoter methylation is <50% of the maximal levels (i.e. at an MtI of <0.25)." (PMID 19568272, 2009). "Our initial work on promoter methylation found CYGB to be significantly methylated in a tumour-specific pattern in around 65% of HNSCC." (PMID 19568272, 2009). "When normalised to the mean from this ‘normal’ epithelium, a wide range of CYGB mRNA expression was observed in tumours (0.14–10.7; mean 1.38)." (PMID 19568272, 2009). "Significant CpG methylation of gene promoters within tumour specimens was found in 28% for p16, 73% for RARβ, 42% for E-cadherin, 65% for cytoglobin and 53% for cyclinA1." (PMID 16449996, 2006). "Cytoglobin is a novel candidate tumour suppressor gene highly methylated in upper aero-digestive tract squamous cancer." (PMID 16449996, 2006). "In OSCC, we now find that the CYGB promoter is significantly methylated in 65% of tumours and, further, that methylation is highly tumour specific (P=0.002)." (PMID 16449996, 2006). "Our data demonstrates tumour-specific promoter methylation is found in a significant proportion of cases at P16, CYGB and CYCA1, while methylation of the promoters of ECAD and RARβ was also seen in surrounding normal tissues." (PMID 16449996, 2006). "Recent evidence indicates that CYGB exerts anti-tumor effects across various human malignancies." (PMID 39227479, 2024). "Furthermore, the promotor region of CYGB exhibits heightened methylation in various types of cancer cell lines and solid tumors in comparison to normal tissues and non-tumor cell lines." (PMID 39227479, 2024). "Additionally, analysis of the GSE13507 dataset indicated a correlation between CYGB expression and tumor pathological grade as well as progression." (PMID 39227479, 2024). "Collectively, these discoveries imply an anti-tumor role for CYGB." (PMID 39227479, 2024). "These include the CYGB gene encoding cytoglobulin, which is a known inhibitor of mitosis and the calcium/calmodulin dependent protein kinase II inhibitor 1 gene (CAMK2N1) that can act as a tumour suppressor and block metastasis." (PMID 37276213, 2023). "In the tumor area, CYGB-positive cells were mostly found surrounding adenocarcinoma." (PMID 35504863, 2022). "Whether the expression of CYGB is upregulated or downregulated depends on the type of tumor cell, the tumor stage, and the tumor microenvironment." (PMID 35397613, 2022). "Thus, the knockdown of CYGB seems to induce cellular changes that lead to a more malignant cancer phenotype, further supporting a tumor-suppressive role for CYGB." (PMID 36009267, 2022). "COL1A1 is considered a downstream product of cytoglobin, which is related to tumor biology and contributes to the adaptive response to oxidative stress and hypoxia/reoxygenation events, thereby promoting lung tumor invasiveness, metastasis, and resistance to treatment." (PMID 35846148, 2022). "Taken together, these findings indicate that CYGB serves a tumor suppressor function." (PMID 35504863, 2022).
tumor (continued). "Furthermore, transcriptome analysis demonstrates the enrichment of multiple cancer malignancy pathways upon CYGB knockdown, supporting a tumor-suppressive role for CYGB." (PMID 36009267, 2022). "Moreover, transcriptome analysis following CYGB knockdown further revealed the enrichment of multiple cancer malignancy pathways, supporting a tumor-suppressive function of CYGB." (PMID 36009267, 2022). "Myoglobin and cytoglobin are tumor suppressors in breast and lung tumors." (PMID 36346805, 2022). "As a family member of globin, CYGB is considered to act as a tumour suppressor." (PMID 33611811, 2021). "Therefore, we investigated if the tumor-suppressive effects of ZDHHC1 work through the CYGB-dependent glucose metabolism regulation pathway." (PMID 32863941, 2020). "Interestingly, Cygb−/− mice developed significantly more tumors than control mice in different organs such as lung and liver, substantiating a tumor-suppressing role of CYGB in vivo." (PMID 30545372, 2018). "We further validated the role of GLUT1 and HXK2 in CYGB-mediated tumor suppression." (PMID 30545372, 2018). "However, conflicting roles for CYGB, either oncogenic or tumor suppressing, have been proposed in lung cancer." (PMID 30545372, 2018). "For example, in tumour microenvironment, CYGB may undergo functional alterations that affect its properties as the regulator of downstream genes." (PMID 28258342, 2017). "As CYGB has been reported to scavenge ROS when overexpressed in tumor cells, CYGB knockdown may raise the cellular ROS level and confer vulnerability that induces cell death." (PMID 24722418, 2014). "Such transcriptional suppressions, which are frequently observed in many cancer types, suggest that CYGB might function as a tumor suppressor gene, making it difficult to discover cancer cell types overexpressing CYGB." (PMID 24722418, 2014). "The range of CYGB expression for tumour-free ‘normal’ epithelium was narrow (0.48–1.61)." (PMID 19568272, 2009). "In clinically derived HNSCC samples, CYGB mRNA expression showed a striking correlation with tumour hypoxia (measured by HIF1A mRNA expression P=0.013) and consistent associations with histopathological measures of tumour aggression." (PMID 19568272, 2009). "However, those tumours with relatively lower levels of CYGB promoter methylation (MtI⩾0.25) showed stronger correlation between expression of CYGB and HIF1A expression." (PMID 19568272, 2009). "Tumour suppressor activity of CYGB has recently been shown in NSCLC and breast cancer cell lines." (PMID 19568272, 2009). "However, all 12 of the tumours with CYGB MtI⩾0.25 had relatively low levels of CYGB mRNA expression and this was irrespective of significant variations in HIF1A expression." (PMID 19568272, 2009). "The epigenetic data presented in this study adds weight to the hypothesis that CYGB is a tumour suppressor gene highly methylated in upper aero-digestive tract squamous cancer." (PMID 16449996, 2006). "Mechanistically, CYGB might exhibit anti-tumor effect by ROS scavenging." (PMID 32908121, 2020). "Furthermore, CYGB is essential for the function of ZDHHC1 as a tumor suppressor in cancer cells." (PMID 32863941, 2020). "Thus, the upregulation of cytoglobin can be indicative of a tumour suppressor ability." (PMID 26339645, 2015). "Recently, it has been proposed that CYGB may function as a tumor suppressor gene as hypermethylation of its promoter was detected in primary human non-small cell lung cancers (48%) and oral cancers (65%), and in lung (8 of 10) and breast (4 of 4) cancer cell lines." (PMID 20828399, 2010).
tumor (continued). "In the current study, we have measured CYGB gene expression and promoter methylation in a series of head and neck tumours and determined associations with histopathology, clinical characteristics and established markers of tumour hypoxia such as HIF1A expression and tumour thickness." (PMID 19568272, 2009). "However, the findings we describe in this paper relating to tumour hypoxia and tumour behaviour may seem to suggest that, in established malignancy, CYGB takes on a role in relation to the response to tumour hypoxia." (PMID 19568272, 2009). "Analyzing from a transcriptomic perspective, CYGB is highly expressed in normal BCa tissues, and patients with BCa with lower CYGB expression have poorer DFS, higher tumor grade, and poorer progression." (PMID 39227479, 2024). "Cytoglobin is a protein present in all cells that not only can transport oxygen and scavenge RONS but also can suppress tumor growth." (PMID 35453573, 2022). "Interestingly, CYGB-positive cells localized in areas surrounding carcinomas but not in the thick fibrotic septum, raising the question of whether activated PSCs migrate to the cancer area to support tumor growth." (PMID 35504863, 2022). "Of the promoters gaining methylation in our sample, many have already been shown to have tumour suppressor activity, including RORa, FAN1, PRDM1, CYGB, L3MBTL4, EPB41L3, with ZNF471 and ZNF671 being specifically silenced by methylation." (PMID 31357948, 2019). "In these cells, CYGB protein expression was increased by 25 and 7.6 fold in MCF7 and MB 231, respectively, which is comparable of the decrease fold in tumor tissues." (PMID 30545372, 2018). "In this work, we have shown the regulation of CYGB expression in HNSCC by both promoter methylation and tumour hypoxia." (PMID 19568272, 2009). "Is the overexpression of CYGB necessary to mediate the hypoxia response, to mediate VEGF expression, to subtend a survival advantage in more aggressive tumours?" (PMID 19568272, 2009). "Similarly, this investigation highlights that CYGB, as a downstream target of SOX7, plays a tumor inhibitory function with SOX7 in BCa." (PMID 39227479, 2024). "Nonetheless, the mechanism of how the CYGB promoter is methylated and how it exerts its tumor-suppressive effects has not been fully elucidated." (PMID 39227479, 2024). "Despite this, the levels of CYGB and NGB proteins were reported to generally be increased in different tumor sections in comparison to levels observed in corresponding normal tissues, leading the authors to suggest a contribution of both globins in promoting cancer survival under oxidative stress." (PMID 34440755, 2021). "Compared to normal tissues, tumor tissues or cell lines have not been extensively investigated for the presence of CYGB." (PMID 24722418, 2014). "On serial section, CYGB, PI3K, p-Akt, IL-6, TNFα and VEGF could be detected in the same area of tumor cells, at least in a part of them." (PMID 23688241, 2013). "It was noted that CYGB promoter methylation in the tumour samples never rose above an MtI of 0.54, whereas the majority of the cell lines (five out of six) showed much higher levels of methylation." (PMID 19568272, 2009). "Clearly more studies are necessary to clarify exactly where CYGB fits in to the cellular hypoxia story and whether it is up- or downstream of HIF1A, currently viewed as the orchestrator of the tumour's response to hypoxia." (PMID 19568272, 2009). "Promoter methylation was significantly elevated in tumours compared to normal tissue for p16 (P=0.048), cytoglobin (P=0.002) and cyclin A1 (P=0.001) but not in RARβ (P=0.088) or E-cadherin (P=0.347)." (PMID 16449996, 2006). "Tumour MtI was significantly higher than that of normal tissue in the case of P16, CYGB and CYCA1 but not RARβ or ECAD (Kruskall–Wallis test of mean rank)." (PMID 16449996, 2006).
tumor (continued). "While in vivo data not always recapitulate in vitro observations, prolonged tumour hypoxia identified in our tissue set may additionally modify the interdependence of CYGB and its proposed downstream effectors." (PMID 28258342, 2017).